AKR1C8 (aldo-keto reductase family 1 member C8)
Synonyms: AKR1C8P; AKR1CL1
Tractability: No criterion of Open Targets' tractability assessment is met for any kind of drug.
Gene: Protein-coding gene on chromosome 10 (5,153,920 to 5,185,187, reverse strand). Ensembl gene ENSG00000264006.
Subcellular location: Cytoplasm
Gene Ontology:
Molecular function: protein binding; alcohol dehydrogenase (NADP+) activity; oxidoreductase activity
Biological process: hormone metabolic process; monocarboxylic acid metabolic process; steroid metabolic process
Cellular component: cytoplasm
Homologues: Orthologues: macaque AKR1C8 (86% identical), pig AKR1C8 (76% identical), rat Akr1c15 (76% identical), zebrafish akr1a1a (42% identical), Drosophila melanogaster CG6083 (38% identical), Caenorhabditis elegans Y39G8B.1 (37% identical), zebrafish zgc:56622 (36% identical), Caenorhabditis elegans Y39G8B.2 (35% identical), Caenorhabditis elegans C07D8.6 (34% identical), zebrafish zgc:110366 (32% identical), tropical clawed frog XB5731323 (31% identical), zebrafish zgc:101765 (29% identical), and 11 more. Paralogues in human: AKR1C1 (67% identical), AKR1C3 (67% identical), AKR1C2 (67% identical), AKR1C4 (66% identical), AKR1D1 (56% identical), AKR1B1 (49% identical), AKR1B10 (47% identical), AKR1B15 (44% identical), AKR1E2 (44% identical), AKR1A1 (41% identical), KCNAB1 (26% identical), KCNAB2 (26% identical), and 4 more.
Diseases named in the same sentence as AKR1C8 in open-access papers:
AKR1C8 is named in the same sentence as 1 disease in open-access papers, as found by Europe PMC text mining. Sharing a sentence is not in itself a finding about the gene and the disease.
AKR1C8 shares sentences with these, for which no sentence is quoted: prostate tumors (1 paper).